TET2 (tet methylcytosine dioxygenase 2)
Diseases named in the same sentence as TET2 in open-access papers (continued):
Sharing a sentence is not in itself a finding about the gene and the disease.
cancer (continued). "Haploinsufficiency of TET2 is a wide spread mutation related to hematological neoplasia, although it is not able to induce cancer alone given that TET2 mutations also occur in healthy groups with clonal hematopoiesis." (PMID 34512655, 2021). "Moreover, activated SIRT1 functions as an inhibitor of Tet2-mediated MDS cell growth, while the SIRT1/Tet2 axis regulates a series of cancer-related genes." (PMID 34222235, 2021). "It is noteworthy that TET2 mutations are present in up to 25% of patients with a diagnosis of myeloid malignancy, and before 2012, no healthy individual had been found with mutations in recognized leukemia driver genes." (PMID 33562056, 2021). "While the role of Tet2 has been studied extensively in the setting of sterile inflammation, chronic diseases and cancer, its function in host antibacterial defense is largely unknown." (PMID 35011643, 2021). "5-hydroxymethylcytosine generated by the activity of TET2 was identified as a predictive biomarker of relapse and survival in cancer patients, suggesting that TET2 could be a potential drug target for slow-cycling cell elimination." (PMID 34135460, 2021). "However, another study in the neck and head tumor revealed that high 5hmC and increased TET2 expression are associated with dormancy and drug resistance to chemotherapy while knockdown of TET2 eliminates the dormant cancer cells." (PMID 34885145, 2021). "With accumulating evidence that impairment of TET2 function may be a major mechanism through which metabolic reprogramming promotes cancer progression, metabolic strategies to enhance TET activity have been investigated." (PMID 34109280, 2021). "TET2 levels was unchanged in 5% HCC specimen compared with para-cancer tissues." (PMID 34019487, 2021). "Another study showed that TET2 plays a key role in controlling the numbers and survival of slow-cycling cancer cells (SCCCs) through controlling the expression of cell death-related genes that regulate TNF-α signaling and restraining its proapoptotic signaling." (PMID 34957093, 2021). "A ZFP engineered with the catalytic domain (CD) of TET2, Ten-Eleven Translocation methylcytosine dioxygenase 2 (ZFP-TET2), was first reported to precisely direct demethylation and reactivation of epigenetically silenced TSGs in cervical and ovarian cancer cells." (PMID 33196851, 2020). "Moreover, it has been shown that silencing TET2 via hypermethylation is a common pathogenetic mechanism in different cancers." (PMID 32066746, 2020). "There may be several potential ways of specifically targeting Tet2 activity in immune-cell subpopulations and cancer cells." (PMID 33184433, 2020). "The targeted NGS panel used in this study, Oncomine Pan‐Cancer, covers the most commonly detected mutations from solid tumors; however, it does not cover the genes that are commonly associated with hematopoietic stem cells, such as DNMT3A, TET2, and ASXL1." (PMID 32449983, 2020). "It would be interesting to study whether Tet2 might be involved in CTLA-4 or PD-1 pathway-mediated immune checkpoint inhibition for cancer treatment." (PMID 33184433, 2020). "In this study, cancer-repopulating cells, when coping with a harsh environment, activate an epigenetic program that leads to the transcription of ten-eleven translocation 2 (Tet2) hydroxymethylating enzyme." (PMID 33193295, 2020). "It is expected that elevating Tet2 activities using specific compounds that enhance or potentiate Tet2 functional roles may be broadly useful in cancer treatment and for the modulation of certain anticancer immune-cell responses." (PMID 33184433, 2020). "Investigations in both mouse models and human clinical samples have demonstrated that Tet2 loss is not essential to cause cancer, but rather influences cancer progression." (PMID 33184433, 2020).
cancer (continued). "Further investigations are necessary to test whether and how Tet2 works together with other Tet proteins in distinct blood cancer cells." (PMID 33184433, 2020). "TET2 protein, which oxidizes 5mC in 5hmC, is frequently loss-of-function-mutated in cancer, especially in myeloid malignancies, but not in MM." (PMID 33138842, 2020). "Despite their effect as potent anti-cancer agents, such TET2 downregulation could be considered a drawback of pan-HDACi in this context." (PMID 32726753, 2020). "Mutations in TET2 (leading to decreased 5-hydroxymethylcytosine levels) have been associated with various hematologic malignancies, although the exact mechanism of how TET2 contributes to the development of such cancers remains unclear." (PMID 31514410, 2019). "They demonstrated that this reduction of 5hmC was the result of glucose-regulated phosphorylation of TET2 by the nutrient and energy sensor AMPK (AMP-activated kinase) and that elevated glucose levels interfere with the expression of numerous cancer-associated genes in a TET2-dependent manner." (PMID 30873122, 2019). "The TET2 protein plays an important role in the epigenetic regulation of gene expression during embryogenesis, differentiation of hematopoietic cells, cancer development, and it is involved in somatic cell reprogramming." (PMID 31231651, 2019). "The distinct properties of the three TET2 promoter elements may play an important role in human cancer development and differentiation and should provide new insights into understanding pathogenesis and development of new therapeutic approaches." (PMID 31231651, 2019). "Notably, there are cell lines with either high or low TET2 expression in the cancer cell lines from most tissues, with the exception of the prostate lines." (PMID 31231651, 2019). "In low grade glioma and subsets of IDH-mutant AML cases in which the presence of 2HG leads to a more benign outcome, we suggest that 2HG contributes to cancer initiation via inhibiting TET2, but suppresses cancer progression/proliferation via inhibiting FTO/MYC signaling." (PMID 29686311, 2018). "Moreover, TET2-mediated demethylation has been shown to influence gene expression in various contexts, including the regulation of oncogenes and tumour suppressor genes in cancer." (PMID 41169875, 2025). "Similarly, data regarding the effects of TET2 on apoptosis are mostly limited to cancer cells." (PMID 37371754, 2023). "In addition to cancer, the role of TET2 dysregulation in development of RDEOs has been explored." (PMID 36814905, 2023). "Notably, TET1 is preserved in its entirety in most cancers without undergoing mutations, unlike TET2, which frequently undergoes somatic mutations." (PMID 38003566, 2023). "Therefore, this study comprehensively evaluated the potential functions of TET2 in different female cancers using data extracted from TCGA, CPTAC, and GEO databases, such as TET2 gene expression features, genetic mutations, DNA methylation, immune infiltration, and gene interactions." (PMID 35223782, 2022). "Finally, four fundamental cancer genotypes are defined: the wild-type (no mutation), the TET2 single mutant, the JAK2 single mutant and the double mutant (in either order)." (PMID 36192425, 2022).
cancer (continued). "Besides, since mutations in TET2 alone are not sufficient for cancer onset, therapy targeting assistant factors, such as other genetic deficiencies and immunostimulation, are also effective treatments." (PMID 34512655, 2021). "In addition, tumors baring a TET2 or IDH-1 mutation may be especially sensitive to VitC treatment, and this is also true for cancer types having high concentrations of labile iron, due to low expression of Ferroportin 1 (Fpn1) for instance." (PMID 34717701, 2021). "Of particular interest were the hypermethylation of DNMT3A, a DNA methylation writer, in five cancer types and TET2, a DNA methylation eraser, in four cancer types, suggesting a possible mechanism in which global DNA methylation changes may be effected via hypermethylation of these targets." (PMID 34871444, 2021). "Therefore, our preclinical data provide a promise to selectively treat cancer patients whose tumors carry deleterious TET2 and nonsynonymous DNMT3A mutations." (PMID 34039392, 2021). "Targeting TET2 and its interactors (e.g., Fe2+, 2-OG, Vitamin C) could regulate the activity of B cells, T cells, and macrophages, which could contribute to immunotherapy of cancer." (PMID 34957093, 2021). "Cancer genome sequencing efforts reveal that in addition to mutations in growth-promoting signaling pathways such as in EGFR and KRAS, chromatin-modifying enzymes and epigenetic regulators such as KMT2D, ARID1A, and TET2 are also frequent targets of genetic alterations." (PMID 34236315, 2021). "Unlike other certain types of cancer, mutation of TET2 is rare in HCC." (PMID 33097695, 2020). "He highlights how Tet2 activity may be modulated to influence cancer immune responses." (PMID 33184433, 2020). "Thus, modulating Tet2 expression levels in M1 macrophages might contribute to cancer-immune therapy." (PMID 33184433, 2020). "Thus, the identification of key genes targeted by TET2 dysregulation may provide further insight into cancer biology." (PMID 30917865, 2019). "Finally, although we did not examine EBF1 because of lack of enrichment of its binding sites in TET-regulated accessible regions of the genome, EBF1 has been shown to increase both chromatin accessibility and DNA demethylation in B progenitor cells, and to interact with TET2 in a cancer cell line." (PMID 27869616, 2016). "This study yields a comprehensive genome-wide view of TET-targeted loci in human cancer cells, revealing for the first time loci that are particularly susceptible to TET-regulated cytosine modifications and identification of distinct and overlapping functions of TET1, TET2, and TET3." (PMID 24958354, 2014). "Collectively, evidence is mounting that TET2 inactivation in cancer may alter more than just DNA methylation; in fact, transformation may result considerably from disrupted interactions with other epigenetic regulators and development-associated transcription factors." (PMID 24622842, 2014). "Although this review focuses on TET2 mutation, there is evidence that mutations in other critical genes can also give rise to a global genomic hypermethylation phenotype in both hematological and nonhematological cancers, including WT1 in AML and IDH1/2 in AML and glioma." (PMID 40116537, 2025).
cancer (continued). "TET1 gene exhibited high methylation levels, whereas TET2 and TET3 genes displayed hypomethylation in most cancers, which correlated closely with patient prognosis." (PMID 39104395, 2024). "Our work uncovers a critical DNMT3a-TET2 coordination that drives HCC resistance to sorafenib, which launches a new era of discovery in the molecular biology of cancer drug resistance." (PMID 38528605, 2024). "DNA methylation or demethylation in cancer is regulated by DNA methyltransferases (DMNTs), which include DMNT1, DMNT3A, and DMNT3B, and the ten-eleven translocation (TET) enzymes TET1, TET2, and TET3, which are known for their roles in cancer." (PMID 38566132, 2024). "We found that KLF3 expression was generally positively correlated with m1A, m5C, and m6A-related gene expression in pan-cancer, especially in YTHDF1, NSUN3, TET2, METTL14, YTHDC2, and FMR1." (PMID 37600783, 2023). "In addition, the β-catenin pathway activator IM12 and the TET2 activator vitamin C were used simultaneously to enhance the effects of TET2 under low-expression conditions, and synergistic inhibitory effects on the growth of cancer were observed both in vitro and in vivo." (PMID 37620362, 2023). "However, the downstream regulatory mechanism of TET2 in cancer remains unclear." (PMID 37667220, 2023). "TET2 can mediate the interferon gamma (IFNγ)-JAK-STAT signaling pathway to control chemokine and PD-L1 expression, lymphocyte infiltration, and cancer immunity." (PMID 37488178, 2023). "Compared to other genes (TET1 and TET2) in the TET family, the functions of TET3 in human cancer remains limited." (PMID 35757739, 2022). "However, TET2 mutation alone is not sufficient to drive malignant disease." (PMID 35393954, 2022). "TET2 was downregulated in 75% HCC specimen and upregulated in 20% HCC specimen compared with para-cancer tissues." (PMID 34019487, 2021). "The m5C regulators with CNV amplification showed significantly increased expression in pan-cancers (such as DNMT3B), and m5C regulators with CNV deletion exhibited remarkably decreased expression, like TET2." (PMID 34325709, 2021). "Our observations in primary T-ALL were supported by analysis of RNA-seq data for 20 T-ALL cell lines from the Cancer Cell Line Encyclopedia (CCLE), which showed a similar distribution of TET2 down-regulation and silencing." (PMID 34413196, 2021). "By assembling the Cancer Cell Line Encyclopedia (CCLE), we found that TETs expression especially TET2 and TET3 was highly expressed in AML cell lines among 40 types of human cancer cell lines." (PMID 32209730, 2020). "As eraser regulators in 5mC methylation, ten-eleven translocation enzymes (TET1, TET2, and TET3) are often downregulated in cancer-inducing DNA demethylation by converting 5mC to 5-hydroxymethylcytosine (5hmC)." (PMID 33195409, 2020). "Finally, I propose key unanswered hypotheses regarding Tet2 in the cancer-immunity cycle." (PMID 33184433, 2020). "Therefore, unlike other certain type of cancer, mutation of TET2 was a rare event in HCC." (PMID 33097695, 2020). "In this paper, we investigated the effect of mutations on DNA methylation modification genes such as DNMT1, DNMT3A, MBD1, MBD4, TET1, TET2, and TET3 through a pan-cancer analysis." (PMID 32093698, 2020). "Among epigenetic genes, DNA methylation related epigenetic modifiers, DNMT1, DNMT3A, MBD1, MBD4, TET1, TET2, and TET3, have been studied related to cancer." (PMID 32093698, 2020). "Variation of Ten-Eleven Translocation (TET) proteins (TET1, TET2 and TET3) is common in human cancers." (PMID 31057717, 2019). "Apart from the upregulation of TET2 and TET3, we also found that there is a significant downregulation of both DNMT3a and DNMT3b expression in cancer tissue compared with normal tissues." (PMID 29983831, 2018). "In these Tet2/3 DKO mice, the hyperproliferation of immature cell types results in malignant transformation and the emergence of cancers, as discussed in more detail below." (PMID 28408905, 2017).
cancer (continued). "The transcription factor EBF1 is an interaction partner of the TET2 gene and is involved in the regulation of DNA methylation in a tissue- and sequence-specific mode of IDH1-mutant cancers." (PMID 27863437, 2016). "U-2 OS harbors mutations in the SLC34A2 (ENST00000382051: c.1538G>T; p.R513L) and TET2 genes (ENST00000380013: c.1394C>T; p.P465L), both of which are of functional relevance in cancers." (PMID 27658049, 2016). "This study represents the first comprehensive genome-wide analysis of the role of TET1, TET2, and TET3 in patterning the distribution of 5mC and 5hmC in human cancer cells." (PMID 24958354, 2014). "Although we did not observe consistent differences at the RNA level for TET1, TET2, or TET3 in lung and brain tumors relative to normal tissue, others have reported lower levels of TET gene expression in cancer." (PMID 23634848, 2013). "By comparing the methylomes of IDH-mutant cancers, the authors identify the transcription factor EBF1 as a partner of TET2, suggesting a possible means for targeting TET2 to specific DNA sequences." (PMID 23863747, 2013). "In TNBC cell lines, the transcription of TET2 could also be repressed by the p65-KDM2A complex, which hampered the expression of E-cadherin and EpCAM, thereby promoting cancer migration." (PMID 40014756, 2025). "To evaluate its function in ATC drug resistance, we examined correlations between the expression of 12 m5C regulators [NSUN2-7, TRDMT1 (writers); ALKBH1, TET2, ALKBH3 (erasers); YBX1 and ALYREF (readers)] and drug sensitivity in the Cancer Therapeutics Response Portal (CTRP)." (PMID 40083919, 2025). "Firstly, utilizing transcriptome data from 33 tumors available in the UCSC Xena database, we conducted an extraction and analysis of the expression profiles of the target genes belonging to the TET family (specifically, TET1, TET2, and TET3) across various types of cancer." (PMID 39104395, 2024). "Despite the negative correlation between TET family genes expression and methylation levels in pan-cancer, unique patterns were observed, such as high methylation of TET1 in most analyzed cancers (except LIHC) and low methylation of TET2 and TET3 in most tumors." (PMID 39104395, 2024). "While it is well known that TET2 converts 5mC into 5hmC, few studies have revealed a negative correlation between 5mC and 5hmC abundance in cancer cells." (PMID 38528605, 2024). "Further, Tet2 knock-out T-cells are observed to preferentially acquire a central memory phenotype, which may contribute to the persistence of TET2 hypomorphic CAR T-cells and maintenance of cancer remission." (PMID 36599826, 2023). "Ct values in TET2 mRNA RT-qPCR on TET2-high cases were not significantly different from those for TET2-low cases; however, both were significantly lower than those for non-cancer tissue." (PMID 34905094, 2022). "On the contrary, TET2 and NSUN4 showed significant lack of m5C modification related CNV mutations among pan-cancers." (PMID 34325709, 2021). "Notably, high BCAT1 expression inversely correlates with survival only in AML patients whose cancers were wild-type for TET2 and IDH, consistent with BCAT1 overexpression promoting tumorigenesis via suppression of TET2 function." (PMID 34109280, 2021). "Future work must also explore how to utilize Tet2 interactors to maintain positive antitumor immune responses and halt negative immune responses against cancers." (PMID 33184433, 2020). "TET2 and EZH2 play important roles in the epigenetic regulation in many cancers." (PMID 32066746, 2020). "Therefore, we investigated the effect of mutations on DNA methylation modification genes such as DNMT1, DNMT3A, MBD1, MBD4, TET1, TET2 and TET3 through a pan-cancer analysis." (PMID 32093698, 2020). "The trend was the same for TET2; TET2 positive cells were fewer in cancer with BRAFV600E (median 60%) than without BRAFV600E (KRASG12/13, median 100%; BRAFWT/KRASWT, median 80%)." (PMID 31842975, 2019).